EGFR (epidermal growth factor receptor)
Diseases named in the same sentence as EGFR in open-access papers (continued):
Sharing a sentence is not in itself a finding about the gene and the disease.
glioma (continued). "Genome-wide alterations involving copy number changes and loss of heterozygosity were identified in 17 glioma samples with positive FISH results for 1p19q co-deletions (n = 9) or EGFR amplification (n = 8)." (PMID 26257825, 2015). "In this study, we aim to examine a panel of molecular markers including IDH1/2 mutation, 1p/19q codeletion, TERTp mutation and EGFR amplification as to their impact on the prognostic value of histological grade in a cohort of lower-grade gliomas." (PMID 26369702, 2015). "Especially ERBB2, being the dimerization partner of EGFR, has previously been associated with glioma risk." (PMID 25537509, 2015). "On the other hand, EGFR gain is significantly rarer overall in IDHmut gliomas (17 % grade II–III, 25 % grade IV) and CDKN2A loss is slightly lower (39 % grade II–III, 42 % grade IV) compared with IDHwt." (PMID 26091668, 2015). "As it is known to be amplified and/or mutated in up to 40% of malignant glioma, EGFR associated with glioma in the Chinese population in some study, was one of the key oncogene subjected to targeted therapy for glioma in China." (PMID 25950430, 2015). "Gefitinib is an EGFR inhibitor that is widely used in the treatment of glioma carrying a mutation in EGFR." (PMID 25950430, 2015). "EGFR gene amplification and mutation occur with high frequency in glioma (40–63 %) and pancreatic cancer (30–50 %)." (PMID 26480820, 2015). "On the other end, IDH1/2 wild-type tumors with either TERTp mutation or EGFR amplification were defined as IDHwt-ET gliomas." (PMID 26369702, 2015). "For example, in the EGFR protein, residue p.A289 is a mutational hotspot in central nervous system cancer, p.C231 is a mutational hotspot in prostate cancer." (PMID 25794154, 2015). "In both studies, additional inhibition of either mTOR by rapamycin or PI3K/mTOR by PI-103 resulted in a sensitizing effect on PTEN mutated glioma cells towards HER1/EGFR inhibition by erlotinib." (PMID 26056598, 2014). "Decorin directly binds and activates EGFR as an EGFR ligand and causes a down-regulation of EGFR and its signaling, leading to a growth inhibition and cell differentiation in certain non-glioma cancer cells." (PMID 24625664, 2014). "The mechanisms underlying EFEMP1's tumor suppressive function in glioma has been shown to be mediated through EFEMP1's binding to EGFR." (PMID 25594013, 2014). "Our results are consistent with previous findings showing a loss of EGFR amplification in primary cultured gliomas." (PMID 25360666, 2014). "One of the most frequently encountered genetic events occurring in high-grade gliomas is the overexpression/amplification/gain-of-function mutation of epidermal growth factor receptor (EGFRvIII) gene." (PMID 25425962, 2014). "Many retrospective studies have shown that polymorphism in EGF or EGFR genes strongly correlates with susceptibility to glioma." (PMID 24740103, 2014). "The ROC curve showed that EGFR amplification is a potential diagnostic marker of Classical gliomas (ROC: AUC = 0.897, P<0.001)." (PMID 24755548, 2014). "Earlier we have shown that Anxa7 is a EGFR negative regulator; its allelic loss has been depicted with enhanced glioma survival signaling pathway." (PMID 24550987, 2014). "As a first result, we confirmed the strong association of IDH mutations with the tumor genomic profile: virtually all 1p19q codeleted tumors are IDH mutated whereas IDH mutation is extremely rare in gliomas with EGFR amplification." (PMID 24877111, 2014). "In gliomas, different types of EGFR aberrations were described – EGFR gene amplification, multiple exon deletion (EGFR variant III), autocrine loop and overexpression – and all of them result in the activation of the receptor." (PMID 23874590, 2013). "For example, the uptake of oncogenic EGFR (or EGFRvIII) mediated by this mechanism causes an apparent phenotypic transformation of indolent glioma cells, and leads to reprograming of growth factor pathways in normal endothelial cells." (PMID 23508692, 2013).
glioma (continued). "The majority of gliomas express EGFR, which is often amplified, rearranged, mutated and/or overexpressed, particularly in malignant tumors." (PMID 23946790, 2013). "Conversely, PDGFRA-low and PDGFRA-intermediate gliomas were associated with significantly higher frequency of EGFR amplification compared to PDGFRA-high gliomas." (PMID 23630597, 2013). "EGFR activation by amplification or mutation is one of the most frequent genetic lesions in gliomas, and higher-grade gliomas are genetically characterised by EGFR amplification." (PMID 23894344, 2013). "The epidermal growth factor receptor has been considered as the hallmark in glioma tumors; thereby, some antibodies have been designed to bind to this receptor and block the downstream signaling pathways." (PMID 24294521, 2013). "This was in striking contrast to the nearly invariable association between gain of EGFR and enriched EGFR expression in the same cohort of glioma samples." (PMID 23630597, 2013). "In the present study, EGFR overexpression correlated with the higher grade gliomas, suggesting that EGFR overexpression was associated with tumor aggressiveness and invasion." (PMID 23946790, 2013). "Treating EGFR expression as a continuous variable only showed a significant association with poor survival in the low grade glioma dataset." (PMID 24312360, 2013). "Overexpression of EGFR in A431 human carcinoma cells and glioma cells causes increased TF expression which functions in tumor initiation and angiogenesis." (PMID 24086497, 2013). "The most frequent mutation in gliomas is the ΔEGFR mutation with the loss of exons 2 to 7 of the EGFR gene, resulting in an in-frame deletion of 267 amino acids in the extracellular domain." (PMID 27408849, 2013). "Poor response to erlotinib monotherapy has been previously attributed to PTEN and EGFR mutations (EGFRvIII) in glioma cells." (PMID 23696788, 2013). "MV variants have been engineered to express IL-13 or a single-chain antibody against the vIII deletion variant of EGFR, therefore re-targeting the viruses against proteins highly expressed on the surface of glioma cells and increasing their oncolytic efficacy." (PMID 24202446, 2013). "Two of the signature genetic events that occur in human gliomas, EGFR amplification and IDH mutation, are poorly represented in experimental models in vitro." (PMID 24349039, 2013). "Nevertheless, alternatively spliced EGFR transcript variants and EGFRvIII mRNA were produced at different levels according to the histological type of glioma." (PMID 22159595, 2012). "Association between EGFR tSNPs and the risk of glioma based on logistic tests and their heterozygote and homozygote odds ratios, per allele odds ratios and confidence intervals." (PMID 22662167, 2012). "A protective effect was also observed for the haplotype “AATT” of the EGFR gene that was associated with a 29% reduction in the risk of developing glioma." (PMID 22662167, 2012). "To investigate potential relationships between EGFR SNP polymorphisms, haplotypes, locus–locus interactions, and their role in the etiology of gliomas, we performed a comprehensive association analysis in a case–control study in the Han Chinese population." (PMID 22662167, 2012). "We will also investigate the association between germline EGFR variants and somatic EGFR mutations, and the relationship between serum EGFR expression and somatic EGFR expression in the same glioma subjects." (PMID 22662167, 2012). "In gliomas, EGFR amplification is often accompanied by structural rearrangements that cause in-frame deletions in the extracellular domain of the receptor (EGFR vIII)." (PMID 23202898, 2012). "These cells were shown to be equally as sensitive as NSCs to transformation with a mutated epidermal growth factor receptor (EGFR), and orthotopic transplantation of transduced cells to mice caused development of high-grade gliomas." (PMID 22348397, 2012).
glioma (continued). "Our study indicated important evidence for the association between EGFR gene polymorphisms and the risk of glioma." (PMID 22662167, 2012). "We identified two susceptibility tSNPs in the EGFR gene that were potentially associated with an increased risk of glioma (rs730437, p = 0.016; OR: 1.32; 95%CI: 1.05–1.66 and rs1468727, p = 0.008; OR: 1.31; 95%CI: 1.04–1.65)." (PMID 22662167, 2012). "In this case–control study in a Han Chinese population, we identified for the first time rs1468727 and rs730437 in the EGFR gene associated with an increased risk of glioma." (PMID 22662167, 2012). "We found that genotype “CC” of rs1468727 in intron 13 of the EGFR gene was associated with the risk of glioma in Chinese patients." (PMID 22662167, 2012). "Our findings in this study provided new evidence for the association between SNPs and haplotypes of the EGFR gene and the risk of glioma." (PMID 22662167, 2012). "In conclusion, our comprehensive analysis of SNPs in the EGFR gene suggests that EGFR genotypes and haplotypes are associated with glioma risk." (PMID 22662167, 2012). "We observed a protective effect of haplotype “AATT” of the EGFR gene, which was associated with a 29% reduction in the risk of developing glioma, while haplotype “CGTC” increased the risk of developing glioma by 36%." (PMID 22662167, 2012). "EGFR haplotype frequencies and the association with the risk of glioma in case and control patients." (PMID 22662167, 2012). "FASN has also been linked to survival in glioma cells with activating EGFR mutations and other tumors." (PMID 22407012, 2012). "Our results, combined with previous studies, suggested an association between the EGFR gene and glioma development." (PMID 22662167, 2012). "The IDH1 mutation is expected to be almost mutually exclusive with EGFR amplification, so glioma cells with IDH1 mutation seem to represent a new group of tumour cells, which cannot be readily analysed in vitro because of their elimination." (PMID 21326241, 2011). "Glioma specific single point missense mutations in the cysteine rich region of EGFR near the mAb806 epitope lead to autoactivation and enhanced tumorigenicity." (PMID 24212795, 2011). "We now show that glioma-associated missense mutations in this region lead to ligand independent activation of EGFR." (PMID 24212795, 2011). "The ECD truncation that produces the de2-7EGFR (or EGFRvIII), the most common EGFR mutation in glioma, generates a free cysteine in this same region." (PMID 24212795, 2011). "So, the EGFR variants are one of the few examples of glioma-specific targets available for directed therapies." (PMID 22091432, 2011). "The IDH1 mutation is expected to be almost mutually exclusive with EGFR amplification, so glioma cells with IDH1 mutations seem to represent a new group of tumour cells, which cannot be readily analysed in vitro because of their elimination." (PMID 21326241, 2011). "Recently, a series of missense mutations in the extracellular domain (ECD) of EGFR were reported in glioma patients." (PMID 24212795, 2011). "The most common EGFR mutation in glioma is the de2-7EGFR, a 267 amino acid deletion of the extracellular domain (ECD)." (PMID 24212795, 2011). "EGFRvIII and PTEN co-expression was associated with response to EGFR TKI in 26 patients out of a cohort of 49 patients with recurrent glioma and a validation set of 33 patients." (PMID 21352589, 2011). "Somatically acquired mutations of EGFR are commonly (∼40%–50%) observed in gliomas, and the EGFR pathway is commonly targeted in this disease." (PMID 20824129, 2010). "Of these mutant forms, EGFR vIII is the most common mutation in gliomas (30-50%) and has been extensively studied since its discovery in 1990." (PMID 21165163, 2010). "The most frequent genetic lesions in gliomas include mutation or amplification of the Epidermal Growth Factor Receptor (EGFR) tyrosine kinase." (PMID 19214224, 2009).
glioma (continued). "As expected in this supervised approach, three-way clustering was the best fit and all but three glioma samples showed stable clustering into signaling classes associated with EGFR, PDGF and NF1-loss." (PMID 19915670, 2009). "For example, recent studies have demonstrated that EGFR inhibitors are attenuated by particular mutations found in glioma cells, such as PTEN loss or RTK co-amplification." (PMID 19214224, 2009). "Glioma-associated EGFR mutant forms show constitutive kinase activity that chronically stimulates Ras signaling to drive cellular proliferation and migration." (PMID 19214224, 2009). "Gliomas, the most common malignant tumors of the nervous system, frequently harbor mutations that activate the epidermal growth factor receptor (EGFR) and phosphatidylinositol-3 kinase (PI3K) signaling pathways." (PMID 19214224, 2009). "The role of the over expressed EGFR (wild type) and the variant (vIII) receptor in malignant progression of glial tumors and their respective impacts on overall survival have been debated in the literature." (PMID 16236164, 2005). "Our results show that EGFR is associated with regulation of telomerase activity in glioma cells, although the mechanism is currently unclear." (PMID 11953893, 2002). "A striking progression has been the joining of atomic markers such as IDH1/2 transformations, MGMT promoter methylation, EGFR amplification/mutations, and 1p/19q codeletion into the symptomatic criteria for gliomas, as laid out by the WHO CNS tumor classifications." (PMID 41311621, 2025). "In conclusion, scutellarin combined with lidocaine suppressed the proliferation and migration and induced the apoptosis of glioma cells, in which the underlying mechanism might be partly associated with the repression in EGFR signaling." (PMID 39888904, 2025). "In glioma cells, EGFR dysregulation may be associated with a mutation of its gene located on chromosome 7p11.2, increased EGFR amount, increased number of gene copies, chromosomal rearrangement, or autocrine activation." (PMID 40428422, 2025). "Thus the aim of this study was to assess IDH mutations and EGFR amplification status in primary and recurrent gliomas using diffusion and perfusion MRI." (PMID 40197845, 2025). "Many EGFR gene alterations have been identified in gliomas, including amplifications, deletions and single nucleotide polymorphisms (SNPs), so it has served as a clinical biomarker in gliomas." (PMID 39888904, 2025). "The association between CBL and EGFR offers a new way to study glioma." (PMID 39130630, 2024). "Erlotinib, a selective EGFR inhibitor, can significantly inhibit the proliferation of glioma cells with the EGFRvIII mutation by reducing EGFRvIII kinase activity, and it has been observed that erlotinib has a good therapeutic effect on adult high-grade gliomas." (PMID 38937742, 2024). "The association between EGFR amplification may serve as a useful biomarker for poor prognosis in glioma patients." (PMID 39375809, 2024). "Notably, the nuclear localization of FABP7 has been linked to glioma progression, particularly in oncogene-mutated aggressive subtypes, such as EGFR-amplified and IDH1 wild-type GBM." (PMID 39596296, 2024). "A number of EGFR inhibitors remain to be tested in terms of glioma PDT association." (PMID 39201395, 2024).
glioma (continued). "This, together with the co-expression of EGFR marker, associated with high malignancy gliomas, supports the possible tumorigenic capacity that the BCAS1+ population could display." (PMID 38275289, 2024). "Our results suggest that the assessment of mRNA BDKRB1, PRKAR1A, MAP2K2, and EGFR by RT-qPCR in samples of patients with gliomas may have diagnostic significance." (PMID 38254732, 2024). "EGFR mutation and amplification are poor prognostic markers for glioma." (PMID 39105794, 2024). "However, an IDH-wild-type tumor, H3-wild-type, with H3 K27me3 loss, EZHIP overexpression, or EGFR mutation is considered a diffuse glioma, H3 K27-altered, grade 4 (pediatric-type high-grade glioma)." (PMID 39057054, 2024). "The most common EGFR mutation in glioma is EGFRvIII mutation caused by deletion of exons 2–7." (PMID 39054543, 2024). "In addition, it has been recently shown that protein expression of EGFR in serum EVs is an effective diagnostic marker of glioma." (PMID 37195369, 2023). "In addition, previous studies have revealed cell subtypes that are associated with glioma progression, and EGFR, NF1, and PDGFRA/IDH1 are markers for the classical, mesenchymal, and proneural types, respectively." (PMID 37371484, 2023). "In glioma, a continuous Egfl7 autocrine flow line was the cause of oncogenic activation of EGFR." (PMID 37480091, 2023). "Furthermore, it has been noted that augmented EGFR expression in gliomas alongside pTERT mutation and/or chromosomal abnormality of chromosomes 7 and 10 can result in seizures in 75% of patients." (PMID 38067243, 2023). "In addition to the most common GBM‐related genes, we also found mutations in the BRAF and EGFR genes, previously shown to be involved in glioma progression." (PMID 34875133, 2022). "EGFR amplifications and mutations were also more frequent in OA gliomas." (PMID 36433963, 2022). "Of all TERT mutated gliomas, 27% showed EGFR amplifications." (PMID 35453544, 2022). "When applied for clinical targeted therapy, the EGFR is usually mutated in patients with glioma." (PMID 35281087, 2022). "Several studies have shown that EGFR variants are associated with the risk of glioma." (PMID 36347915, 2022). "This study suggests that specific loci in EGFR are associated with an increased risk of glioma." (PMID 36347915, 2022). "The patients with glioma in the LMG high-risk group showed high sensitivity to EGFR inhibitors." (PMID 36698888, 2022). "Interestingly, the GSEA analysis using the CGGA database indicated that high ZC3H15 expression was positively associated with EGFR signaling genes in glioma." (PMID 35027542, 2022). "EGFR amplification is a phenomenon of IDH wildtype TERT mutated high-grade gliomas." (PMID 35453544, 2022). "EGFR has been shown to be overexpressed, amplified, and/or mutated in glioma." (PMID 36400876, 2022). "In addition to the amplification, rearrangement of the EGFR gene and its encoded protein EGFR variants are also common in gliomas." (PMID 36338770, 2022).